TAF11L9 (TATA-box binding protein associated factor 11 like 9)
Gene: Protein-coding gene on chromosome 5 (17,593,798 to 17,594,394, reverse strand). Ensembl gene ENSG00000283988.
Gene Ontology:
Molecular function: RNA polymerase II general transcription initiation factor activity; protein heterodimerization activity
Biological process: RNA polymerase II preinitiation complex assembly; transcription initiation at RNA polymerase II promoter
Cellular component: transcription factor TFIID complex; nucleus
Homologues: Orthologues: tropical clawed frog taf11 (45% identical), zebrafish taf11 (44% identical), Drosophila melanogaster Taf11 (42% identical), Caenorhabditis elegans taf-11.1 (33% identical), Caenorhabditis elegans taf-11.2 (27% identical). Paralogues in human: TAF11L10 (99% identical), TAF11L5 (99% identical), TAF11L6 (99% identical), TAF11L7 (99% identical), TAF11L8 (99% identical), TAF11L3 (99% identical), TAF11L4 (99% identical), TAF11L13 (94% identical), TAF11L2 (91% identical), LINC02218 (87% identical), TAF11L12 (87% identical), TAF11L11 (84% identical), and 2 more.